LCN9 (lipocalin 9)
Synonyms: HEL129
Tractability: Antibody: UniProt places it where antibodies can reach, with medium confidence; UniProt predicts a signal peptide or a membrane-spanning region; its Gene Ontology location is reachable by antibodies, with medium confidence.
Gene: Protein-coding gene on chromosome 9 (135,663,309 to 135,666,961, forward strand). Ensembl gene ENSG00000148386.
Subcellular location: Secreted
Pathways (Reactome):
Transport of small molecules: Transport of fatty acids
Gene Ontology:
Molecular function: protein binding; small molecule binding
Cellular component: extracellular region
Genetic constraint (gnomAD): Loss-of-function variants: 22 observed, 16.21 expected, observed/expected ratio (o/e) 1.36, 90% interval 0.96 to 1.84. The upper end of that interval is the gene's LOEUF score, 1.84, which puts it in group 6 of 6, group 1 being the genes least tolerant of losing a copy. Missense variants: 202 observed, 195.62 expected, observed/expected ratio (o/e) 1.03, 90% interval 0.92 to 1.16. Synonymous variants: 89 observed, 80.66 expected, observed/expected ratio (o/e) 1.1, 90% interval 0.93 to 1.32.
Homologues: Orthologues: chimpanzee LCN9 (87% identical), macaque LCN9 (83% identical), dog LCN9 (61% identical), mouse Lcn9 (54% identical), rat Lcn9 (45% identical). Paralogues in human: PAEP (24% identical), LCN1 (24% identical), LCN15 (22% identical), LCN2 (22% identical), OBP2B (22% identical), LCN10 (20% identical), LCN6 (19% identical), OBP2A (19% identical), PTGDS (19% identical), LCN12 (17% identical), LCNL1 (13% identical), LCN8 (13% identical).
Diseases named in the same sentence as LCN9 in open-access papers:
LCN9 is named in the same sentence as 3 diseases in open-access papers, as found by Europe PMC text mining. Sharing a sentence is not in itself a finding about the gene and the disease. The quoted sentences say what the papers report.
infertile (3 papers, 2021 to 2024). "For example, the lipocalin family quintuple KO (Lcn5 and Lcn9 included) males were mostly infertile with a reduced amount of mature ADAM3, which is an essential protein for sperm binding to the zona pellucida." (PMID 37324270, 2023). "While the Lcn9 single KO did not affect male fertility, the quadruple KO and quintuple KO male mice were subfertile and mostly infertile, respectively, with a reduced amount of ADAM3, an essential protein for sperm binding to the zona pellucida." (PMID 36428102, 2024).
LCN9 also shares sentences with these, for which no sentence is quoted: bacterial infections (1 paper); cancer (1).